OCLN (occludin)
Diseases named in the same sentence as OCLN in open-access papers (continued):
Sharing a sentence is not in itself a finding about the gene and the disease.
interstitial lung disease (1 paper, 2026). A diverse group of lung diseases that affect the lung parenchyma. "We demonstrate that the RET inhibitor pralsetinib (Pral) induces fatal interstitial lung disease by inhibiting FGFR1, not RET, leading to the selective loss of occludin (OCLN)." (PMID 42088419, 2026).
Interstitial pneumonitis (1 paper, 2019). "Lungs similarly are characterized by tissue changes reflecting inflammation, including interstitial pneumonitis, an influx of macrophage and eosinophils, and disrupted occludin protein and barrier function." (PMID 31774879, 2019).
intestinal atresia (1 paper, 2021). A congenital malformation characterized by the absence of a normal opening in a part of the intestine. "Compared with the control group, which consisted of patients with congenital intestinal atresia, the NEC patients showed significantly decreased expression of occludin." (PMID 33482929, 2021).
intestinal tumors (1 paper, 2025). "ZO proteins, particularly ZO-1, link occludin to the actin cytoskeleton and play a vital role in maintaining tight junction integrity, reducing the risk of intestinal tumors and related disease." (PMID 40078994, 2025).
Intraventricular hemorrhage (1 paper, 2023). Bleeding into the ventricles of the brain. "A significant difference in serum OCLN concentrations was noticed in pregnancies complicated by the early-onset FGR, in relation to the intraventricular hemorrhage (IVH) occurrence in newborns." (PMID 36768287, 2023).
iron deficiency (1 paper, 2024). "In this study, iron deficiency and iron overload resulted in downregulation of the tight junction proteins Occludin and Claudin-1 as well as the mucosal proteins MUC1 and MUC2 in jejunum mucosa, which may contribute to a greater susceptibility of neonates to pathogen infection." (PMID 39127747, 2024).
Jaundice (1 paper, 2016). Yellow pigmentation of the skin due to bilirubin, which in turn is the result of increased bilirubin concentration in the bloodstream. "Duodenal biopsies taken at the time of ERCP in patients with jaundice demonstrated significant reductions in villus height and occludin expression when compared with controls." (PMID 27252406, 2016).
kidney transplant (1 paper, 2022). A surgical procedure in which one or both kidneys from a donor are implanted into a recipient. "Immunofluorescent staining of subcutaneous fat biopsies from kidney transplant recipients, and controls, were used to measure microvascular expression of tight-junction proteins (claudin-5, occludin, JAM-1), and control microvasculature for TMAO effects." (PMID 35292710, 2022).
metastasis (1 paper, 2022). The spread or migration of cancer cells from one part of the body (where they first appeared) to another. "Similar to GBM, decreased expression of the TJ protein occludin in brain metastasis contributes to the higher permeability of the BBB and the formation of peritumoral brain edema." (PMID 35910247, 2022). "Decreased expression of occludin was found not only in the tumor cells themselves but also in non-neoplastic endothelial cells adjacent to brain metastasis." (PMID 35910247, 2022).
metastatic disease (1 paper, 2012). "Knockdown of occludin resulted in increased invasion, reduced adhesion and significantly reduced TJ functions, whilst Q-RT-PCR showed occludin to be significantly decreased in patients with metastatic disease." (PMID 22559840, 2012).
migraine (1 paper, 2025). "A recent Italian study on a cohort of pediatric migraine patients showed higher levels of plasma occludin and IgA, associated with increased intestinal permeability, and an increase in plasma LPS, indicating low-grade intestinal inflammation compared to healthy controls." (PMID 39861467, 2025).
MPS III A (1 paper, 2013). "Differences in reductions of tight junction protein expressions in brain structures were determined between MPS III A and III D. Occludin expression was mainly reduced in putamen and hippocampus of MPS III A patient and in primary motor cortex of MPS III D patient." (PMID 24225396, 2013).
MPS III D (1 paper, 2013). "In brain tissues from the MPS III D patient, a major decrease of occludin expression was seen only in primary motor cortex and claudin-5 – in hippocampus and cerebellum." (PMID 24225396, 2013).
Multiple Organ Failure (1 paper, 2020). A progressive condition usually characterized by combined failure of several organs such as the lungs, liver, kidney, along with some clotting mechanisms, usually postinjury or postoperative. "Brain tissue samples were available in 47 autopsies, of which 38% (18/47) had no expression of occludin in the endothelium of cerebral microvessels, 34% (16/47) developed multiple organ failure before death, and 74.5% (35/47) had septic shock." (PMID 32600371, 2020).
neovascular glaucoma (1 paper, 2024). "In neovascular glaucoma due to RVO, the VEGF-VEGFR2 pathway suppresses occludin, causing damage to intercellular tight junctions, and activates MMP-9, resulting in the destruction of the blood–retinal barrier." (PMID 39272767, 2024).
neuroendocrine neoplasm (1 paper, 2025). Endocrine tumors, also referred to as neuroendocrine tumors (NETs), are defined by a common phenotype which is characterized by the expression of general markers (neuron specific enolase, chromogranin, synaptophysin) and hormone secretion products. "Although occludin expression could be found in almost every tumor entity, occludin positivity was most seen in adenocarcinomas and in neuroendocrine neoplasms." (PMID 40173205, 2025).
non-small cell lung carcinoma (1 paper, 2025). A group of at least three distinct histological types of lung cancer, including non-small cell squamous cell carcinoma, adenocarcinoma, and large cell carcinoma. "Exosomal miR-3157-3p from non-small cell lung carcinoma (NSCLC) cells promotes pre-metastatic niche formation, angiogenesis, and increased vascular permeability by targeting tissue inhibitor of metalloproteinase (TIMP)/KLF2, which regulates the expression of VEGF, MMP2, MMP9, and occludin in ECs." (PMID 40002766, 2025).
obsessive-compulsive disorder (1 paper, 2024). A disorder characterized by the presence of persistent and recurrent irrational thoughts (obsessions), resulting in marked anxiety and repetitive excessive behaviors (compulsions) as a way to try to decrease that anxiety. "The aim of this study is to investigate whether the levels of zonulin and occludin, tight junction proteins in the intestinal epithelium, change in obsessive-compulsive disorder (OCD) patients and whether they differ between OCD patients with and without MDD." (PMID 39109367, 2024). "The aim of this study is to determine whether the levels of zonulin and occludin, tight junctions (TJ) proteins in the intestinal epithelium, will differ between obsessive compulsive disorder (OCD) patients and healthy controls." (PMID 39109367, 2024).
oral lichen planus (1 paper, 2025). Oral lichen planus is a chronic inflammatory oral condition of unknown aetiology characterized by T-cell-mediated chronic immune response and abnormal epithelial keratinization cycle. "In contrast, decreased oral mucosal occludin gene expression has also been associated with various pathological states, including increased severity of oral lichen planus." (PMID 39996934, 2025).
Peptic ulcer (1 paper, 2015). The term peptic ulcer refers to acid peptic injury of the digestive tract, resulting in mucosal break reaching the submucosa. "Despite this finding, when the associations between the peptic ulcer-related factors and climate were studied, it was found that the expression of occludin, NOS and EGFR was significantly lower in the extreme cold climate than that in the extreme hot climate." (PMID 25452787, 2015).
pharyngitis (1 paper, 2021). Inflammation of the throat most often caused by viral and bacterial infections. "Moreover, OCLN expression was significantly higher in AR patients with pharyngitis (p = 0.011) compared with patients without pharyngitis." (PMID 33441633, 2021).
pouchitis (1 paper, 2023). Acute inflammation in the intestinal mucosa of the continent ileal reservoir (or pouch) in patients who have undergone ileostomy and restorative proctocolectomy (proctocolectomy, restorative). "The rat model of pouchitis showed increased pouch inflammation, increased CD3+ and CD45+ T cell infiltration, and decreased tight junction proteins, including ZO-1 and Occludin." (PMID 38137976, 2023).
prediabetes (1 paper, 2022). "Likewise, plasma from hyperglycemic clamped individuals with prediabetes, showed decreased occludin levels." (PMID 36127330, 2022).
primary immunodeficiency (1 paper, 2023). "GO and KEGG enrichment analysis indicated that OCLN may be involved in a variety of immune activities such as humoral immune response, B cell receptor signaling pathway, immunoglobulin complex circulating and primary immunodeficiency." (PMID 37809090, 2023).
prostate tumor (1 paper, 2017). "In particular, we found primarily overexpression of CTNNB1, CDH1, SMAD2, SMAD3, TCF3, LEF1 in younger patients and overexpression of SNAI1 and underexpression of KRT5, KRT19, OCLN, CDH2 and MUC1 which clearly indicates different characteristics of prostate tumor in younger vs older patients." (PMID 29206234, 2017).
rhinitis (1 paper, 2024). An inflammation of the mucous membrane lining the nose, usually associated with nasal discharge. "Treatment of HNECs with IL-4 and IL-13, which are highly concentrated in the nasal epithelium of rhinitis patients, decreases the expression of ZO-1 and Occludin, components of tight junctions." (PMID 39108557, 2024).
rosacea (1 paper, 2025). A chronic erythematous skin disorder that affects the face. "Compared with healthy controls, KRT6A and KRT16 mRNA levels were significantly upregulated in rosacea, whereas CLDN1, CLDN16, OCLN, and KRT17 showed no significant changes, and CLDN23 was significantly downregulated." (PMID 40346694, 2025).
sarcomatoid mesothelioma (1 paper, 2024). A diffuse malignant mesothelioma arising from the pleura and less often the peritoneum. "Whether occludin is differentially expressed in epithelioid and sarcomatoid mesothelioma cannot be resolved in the present study, as the vast majority of cases, including all effusions, had epithelioid differentiation." (PMID 38141113, 2024).
severe acute respiratory syndrome (1 paper, 2022). A viral respiratory infection caused by the SARS coronavirus. "It has been reported that bicellular tight junction proteins, such as OCLN, CLDNs, and JAM-A, are receptors for adenovirus, papillomavirus, rotavirus, influenza virus, severe acute respiratory syndrome (SARS), and HIV-1." (PMID 36291839, 2022).
thrombosis (1 paper, 2023). "By photochemically induced thrombosis model, the expression of occludin was decreased in brain endothelial cells from ischemic lesions." (PMID 36806348, 2023).
thyroid tumor (1 paper, 2023). A benign or malignant neoplasm affecting the thyroid gland. "Our study provides evidence that OCLN, ZNF423, LYG1, and AQP5 mRNA markers can serve as reliable molecular markers for identifying NIFTP among other thyroid tumors." (PMID 37658903, 2023). "Our results suggest that OCLN, ZNF423, LYG1, and AQP5 mRNA markers might serve as reliable molecular markers for identifying NIFTP among other thyroid tumors, ultimately aiding in accurate diagnosis and management of NIFTP patients." (PMID 37658903, 2023).
tongue cancer (1 paper, 2009). A malignant neoplasm affecting the tongue. "They analysed the distribution of claudins (1, 4, 5, and 7) and occludin in 97 patients with superficial and invasive front of tongue cancer, and found that claudins 1 and 7 were strongly expressed, claudin 4 moderately expressed, and claudin 5 the least expressed; occludin staining was irrelevant." (PMID 19696947, 2009).
tongue squamous cell carcinoma (1 paper, 2016). A squamous cell carcinoma that arises from the tongue. "The expression of occludin in our study is mostly negative which corresponds with study in tongue squamous cell carcinoma." (PMID 27398181, 2016).
toxoplasmosis (1 paper, 2023). A parasitic disease contracted by the ingestion or fetal transmission of toxoplasma gondii. "More importantly, ALA treatment observably increased the expression levels of occludin, further implying the therapeutic effect of ALA on toxoplasmosis." (PMID 38087373, 2023).
transient ischemic attack (1 paper, 2023). A brief attack (from a few minutes to an hour) of cerebral dysfunction of vascular origin, with no persistent neurological deficit. "As a potential marker of transient ischemic attack (TIA), miR-122-5p targets OCLN to regulate the apoptosis and permeability of brain microvascular endothelial cells (BMECs)." (PMID 37841310, 2023).
type 1 diabetic (1 paper, 2024). "They found that APS-1 significantly reduced insulin levels in type 1 diabetic (T1D) mice and improved the intestinal barrier function by regulating the expression of ZO-1, Occludin, and Claudin-1." (PMID 39215362, 2024).
uremia (1 paper, 2025). A clinical syndrome associated with the retention of renal waste products or uremic toxins in the blood. "In addition, NEAT1/miR-122-5p/Occludin axis, as a promising therapeutic target, will provide new ideas and methods for reducing complications and improving quality of life in patients with uremia." (PMID 40338929, 2025).
vaginitis (1 paper, 2023). A non-infectious or infectious inflammatory process affecting the vagina. "Vitamin D also reduced postmenopausal vaginitis by enhancing the expression of occludin and E-cadherin tight junction proteins, enhances intercellular adhesion, and regulating the vaginal microbiota in ovariectomised rats." (PMID 37764381, 2023).
vasculitis (1 paper, 2023). "Moreover, recent experimental data demonstrated defective intestinal barrier with decreased expression of tight junction proteins such as Occludin, Claudin-3, and ZO-1 in LCWE-induced KD vasculitis model, and IVIG treatment could improve gut leakage to alleviate cardiovascular injuries." (PMID 37398673, 2023).
vitiligo (1 paper, 2022). Generalized well circumscribed patches of leukoderma that are generally distributed over symmetric body locations and is due to autoimmune destruction of melanocytes. "Multispectral immunohistochemistry confirmed that OCLN expression significantly increased in the fibroblasts of vitiligo patients." (PMID 35222802, 2022). "Meanwhile, occludin was upregulated in melanocytes located in perilesions of vitiligo patients compared to healthy controls." (PMID 35222802, 2022). "Previous sequencing results reported by our group showed that OCLN expression was upregulated in vitiligo patients." (PMID 35222802, 2022). "Previously, we performed transcriptome sequencing of CD8+ T cells and found upregulation of OCLN in CD8+ T cells in vitiligo skin lesions." (PMID 35222802, 2022). "Our study results suggested a critical role for OCLN in the occurrence, progression, and maintenance of vitiligo." (PMID 35222802, 2022). "The sequencing results showed that the OCLN gene was significantly upregulated in the CD8+ T cells from vitiligo skin lesions." (PMID 35222802, 2022). "In this study, we confirmed that the expression level of OCLN was significantly increased in CD8+ T cells of vitiligo patients by qPCR, Western blotting, and multispectral immunohistochemistry." (PMID 35222802, 2022). "This study demonstrated that OCLN gene expression was elevated in the CD8+ T cells of vitiligo patients, and occludin mediates the adherence of CD8+ T cells to melanocytes." (PMID 35222802, 2022). "In this study, we examined the expression level of OCLN in CD8+ T cells from vitiligo patients and normal controls." (PMID 35222802, 2022). "Occludin was significantly upregulated in the fibroblasts from vitiligo patients compared to healthy controls." (PMID 35222802, 2022). "Previous transcriptome sequencing results published by our group showed that the occluding (OCLN) gene was significantly upregulated in CD8+ T cells from skin lesions of vitiligo." (PMID 35222802, 2022). "HIF-1α was also highly expressed in fibroblasts under the hypoxic environment, which may explain the increased OCLN expression in the fibroblasts from vitiligo patients." (PMID 35222802, 2022). "In addition, CD8 and OCLN markers were used to double stain the vitiligo skin lesions and normal skin tissues using multispectral immunohistochemistry." (PMID 35222802, 2022). "In this regard, we found that fibroblasts from vitiligo patients significantly express occludin, which may participate in the continuous retention of CD8+ T cells in the skin lesions." (PMID 35222802, 2022). "In summary, OCLN plays an important role in the occurrence and maintenance of vitiligo, and OCLN may be a potential treatment target of vitiligo." (PMID 35222802, 2022). "Interestingly, OCLN was upregulated in melanocyte precursors of vitiligo patients via transcriptome sequencing." (PMID 35222802, 2022). "Keratinocytes from both vitiligo patients and normal controls had highly expressed occludin." (PMID 35222802, 2022). "OCLN may also participate in maintaining the residence of Trm in the vitiligo skin lesions, which explains why vitiligo always recurs at the same location." (PMID 35222802, 2022). "This suggests that OCLN might be involved in the pathogenesis of vitiligo." (PMID 35222802, 2022). "Thus, occludin was upregulated in vitiligo via the HIF-1α signaling pathway." (PMID 35222802, 2022). "Real-time PCR and Western blotting were used to verify the consistency of OCLN mRNA and protein expression levels in CD8+ T cells from vitiligo patients' peripheral blood mononuclear cells (PBMCs)." (PMID 35222802, 2022). "Oxidative stress in vitiligo drives increased HIF-1α expression, and HIF-1α overexpression and enhancement upregulate occludin expression, which mediates the adhesion of CD8+ T cells to melanocytes." (PMID 35222802, 2022).
vitiligo (continued). "The pathogenesis of vitiligo is closely related to oxidative stress, and our data suggest that overexpression of hypoxia-inducible factor-1α (HIF-1α) increases the expression of occludin." (PMID 35222802, 2022). "Thus, oxidative stress in vitiligo drives increased HIF-1α expression in CD8+ T cells, and HIF-1α overexpression and enhancement upregulate occludin expression, which mediates the adhesion of CD8+ T cells to melanocytes." (PMID 35222802, 2022). "Therefore, we assumed that CD8+ T cells from PBMCs of vitiligo patients migrate to the skin, where occludin on the surface of CD8+ T cells may bind to the occludin on the surface of melanocytes to mediate the adhesion of CD8+ T cells and melanocytes." (PMID 35222802, 2022).
Zinc deficiency (1 paper, 2020). A deficiency of the essential metal Zinc; an essential cofactor for many enzymes. "In Caco-2 cells, zinc deficiency leads to the downregulation of OCLN and ZO-1, and zinc supplementation increases TEER and induces expression of CLDN-2, -7 and ZO-1." (PMID 33182652, 2020).